CENPN (centromere protein N)
Description:
Component of the CENPA-NAC (nucleosome-associated) complex, a complex that plays a central role in assembly of kinetochore proteins, mitotic progression and chromosome segregation. The CENPA-NAC complex recruits the CENPA-CAD (nucleosome distal) complex and may be involved in incorporation of newly synthesized CENPA into centromeres. CENPN is the first protein to bind specifically to CENPA nucleosomes and the direct binding of CENPA nucleosomes by CENPN is required for centromere assembly. Required for chromosome congression and efficiently align the chromosomes on a metaphase plate.
Synonyms: CENP-N; C16orf60; ICEN32; FLJ13607; FLJ22660; BM039
Tractability: PROTAC: ubiquitination databases record sites on it.
Gene: Protein-coding gene on chromosome 16 (81,006,506 to 81,033,114, forward strand). Ensembl gene ENSG00000166451.
Subcellular location: Nucleus; Chromosome, centromere, kinetochore
Subcellular location (Human Protein Atlas): Nucleoplasm
Pathways (Reactome):
Cell Cycle: Amplification of signal from unattached kinetochores via a MAD2 inhibitory signal; Deposition of new CENPA-containing nucleosomes at the centromere; EML4 and NUDC in mitotic spindle formation; Mitotic Prometaphase; Resolution of Sister Chromatid Cohesion; Separation of Sister Chromatids
Signal Transduction: RHO GTPases Activate Formins
Gene Ontology:
Biological process: chromosome segregation; CENP-A containing chromatin assembly
Cellular component: inner kinetochore; nucleoplasm; cytosol; nucleus
Genetic constraint (gnomAD): Loss-of-function variants: 21 observed, 24.06 expected, observed/expected ratio (o/e) 0.87, 90% interval 0.62 to 1.26. The upper end of that interval is the gene's LOEUF score, 1.26, which puts it in group 5 of 6, group 1 being the genes least tolerant of losing a copy. Missense variants: 255 observed, 248.42 expected, observed/expected ratio (o/e) 1.03, 90% interval 0.93 to 1.14. Synonymous variants: 114 observed, 90.97 expected, observed/expected ratio (o/e) 1.25, 90% interval 1.08 to 1.46.
Homologues: Orthologues: macaque CENPN (97% identical), chimpanzee CENPN (92% identical), dog CENPN (86% identical), pig CENPN (84% identical), rabbit CENPN (83% identical), guinea pig CENPN (77% identical), mouse Cenpn (73% identical), rat Cenpn (59% identical), tropical clawed frog cenpn (52% identical), zebrafish cenpn (33% identical).
Diseases named in the same sentence as CENPN in open-access papers:
CENPN is named in the same sentence as 29 diseases in open-access papers, as found by Europe PMC text mining. Sharing a sentence is not in itself a finding about the gene and the disease. The quoted sentences say what the papers report.
breast carcinoma (9 papers, 2021 to 2025). "Recent studies have reported that CENPN is associated with the invasion and metastasis of glioma, breast cancer and other cancers." (PMID 40458725, 2025). "A number of human diseases have been associated with Centromere protein N (CENPN), but its role in breast cancer is unclear." (PMID 37697245, 2023). "In other types of tumors, studies have shown that CENPN can also promote the metastasis of gliomas, breast cancer and other cancers." (PMID 40458725, 2025). "Bioinformatic analysis and cellular tests used in our work have demonstrated that CENPN is overexpressed in a range of malignancies, including breast cancer, and that this overexpression has a significant impact on patient prognosis." (PMID 37697245, 2023). "Breast cancer cells' malignant characteristics, such as migration and cell proliferation, were inhibited by CENPN knockdown." (PMID 37697245, 2023). "Using the CCK8 test and colony formation assay, CENPN was evaluated for its ability to inhibit breast cancer cell proliferation." (PMID 37697245, 2023). "According to these findings, breast cancer tumor immunosuppression is strongly correlated with increased CENPN expression." (PMID 37697245, 2023). "Transwell assays and scratch tests were used to assess the impact of CENPN on breast cancer cell migration." (PMID 37697245, 2023). "Using TCGA clinical survival data and breast cancer specimens from our center for validation, the relationship between CENPN expression, breast cancer prognosis, and clinicopathological characteristics of patients was examined." (PMID 37697245, 2023). "Transwell test and scratch assay results also showed that CENPN silencing dramatically reduced breast cancer cells' capacity to migrate." (PMID 37697245, 2023). "The findings revealed that patients with high CENPN expression in breast cancer had a poor prognosis." (PMID 37697245, 2023). "The overexpression of CENPN in breast cancer was verified at the transcriptional and translational levels in breast cancer specimens collected at our center, respectively." (PMID 37697245, 2023). "Our study's limitation is that more long-term follow-up data are required for further validation of the utility of CENPN for anticipating immunotherapy in breast cancer." (PMID 37697245, 2023). "CENPN may be an oncogene for breast cancer as it stimulates cell proliferation, as well as a potential target for immune checkpoint inhibitor therapy." (PMID 40384436, 2025). "CENPN is found in a wide range of tumors, including breast cancer." (PMID 37697245, 2023). "According to our findings, CENPN may be an oncogene in breast cancer, as well as a new therapeutic target for immune checkpoint inhibitors." (PMID 37697245, 2023). "CENPN is an important predictor for both breast carcinoma recurrence and mortality among smokers." (PMID 33313822, 2021). "Studies have shown that abnormal expression of CENPN is related to the pathogenesis of NPC, breast cancer, and oral squamous cell carcinoma." (PMID 37776538, 2024). "Furthermore, we check the expression of CENPN in other breast cancer cell lines and discovered that, in contrast to MCF-10A cells, which represent normal breast cells, CENPN was highly expressed in 468, 231, MCF-7, and SKBR3 cells." (PMID 37697245, 2023). "However, the role of CENPN in breast cancer has not been revealed." (PMID 37697245, 2023). "Our research found that CENPN overexpression lowered the aggregation of antitumor immune cells (CD8 + T cells and NKs) and boosted the infiltration of immunosuppressive cells (Tregs and Th2 cells) within breast cancer, which may be the mechanism of its encouragement of breast tumor development." (PMID 37697245, 2023).
nasopharyngeal carcinoma (8 papers, 2021 to 2025). A carcinoma arising from the nasopharyngeal epithelium. "Given the poor prognosis caused by nasopharyngeal carcinoma metastasis, we focused on the relationship between CENPN expression and metastasis-related biological behaviors." (PMID 40458725, 2025). "We established a nude mouse model of metastatic tumors by injecting nasopharyngeal carcinoma cells through the tail vein to investigate the effect of CENPN expression on nasopharyngeal carcinoma metastasis in vivo." (PMID 40458725, 2025). "We first performed immunofluorescence staining of 5-8F cells to explore the detailed molecular mechanism by which CENPN promotes nasopharyngeal carcinoma metastasis, and the results revealed that CENPN and STAT3 were colocalized." (PMID 40458725, 2025). "Our previous study revealed that CENPN is closely related to the malignant biological behaviors of nasopharyngeal carcinoma (NPC) cells, such as glucose metabolism, autophagy, and radioresistance." (PMID 40458725, 2025). "We used oeCENPN cells to further verify the effect of CENPN expression on promoting the invasion and metastasis of nasopharyngeal carcinoma cells." (PMID 40458725, 2025). "Transwell assays confirmed that stattic significantly inhibited the effect of CENPN overexpression on promoting the invasion and metastasis of nasopharyngeal carcinoma cells." (PMID 40458725, 2025). "First, we investigated the effects of CENPN knockdown on nasopharyngeal carcinoma cells and found that, compared with the control cells, the CNE-2Z and 5-8F cell lines presented significant decreases in invasion and migration after CENPN knockdown." (PMID 40458725, 2025). "The invasion and migration capacities of nasopharyngeal carcinoma cells decreased significantly after CENPN knockdown, whereas the overexpression of CENPN significantly promoted the invasion and metastasis abilities of nasopharyngeal carcinoma cells." (PMID 40458725, 2025). "The results of the CCK8 assay measured at 450 nm and the percentage of EdU-positive cells revealed that CENPN expression significantly promoted the proliferation of nasopharyngeal carcinoma cells." (PMID 40458725, 2025). "Next, we studied the relationships between the expression of CENPN and the clonogenic and proliferative abilities of nasopharyngeal carcinoma cells." (PMID 40458725, 2025). "Transcriptomic sequencing of shCENPN and shNC nasopharyngeal carcinoma cells revealed that USP37 expression was significantly reduced after CENPN knockdown." (PMID 40458725, 2025). "Our previous studies showed that CENPN can promote the malignant biological behaviors of nasopharyngeal carcinoma cells and is closely related to the pathogenesis of nasopharyngeal carcinoma." (PMID 40458725, 2025). "In this study, we conducted in vivo and in vitro experiments to investigate the role of CENPN in regulating the invasion and metastasis capacities of nasopharyngeal carcinoma cells." (PMID 40458725, 2025). "Two nasopharyngeal carcinoma cell lines with stable CENPN knockdown and overexpression were constructed, and changes in their proliferation, invasion and metastasis capacity were detected." (PMID 40458725, 2025). "The CENPN/STAT3/USP37 axis is expected to provide a new therapeutic target for nasopharyngeal carcinoma metastasis." (PMID 40458725, 2025). "Past studies have shown that CENPN is overexpressed in lung adenocarcinoma and promotes its tumor progression,CENPN also promotes malignant biological behavior in nasopharyngeal carcinoma cells by enhancing aerobic glycolysis." (PMID 37697245, 2023). "Investigating the impact of centromere protein N (CENP-N) on radiosensitivity of nasopharyngeal carcinoma (NPC) cells." (PMID 37940975, 2023). "The CENPN/STAT3/USP37 axis is expected to be a new target for nasopharyngeal carcinoma treatment." (PMID 40458725, 2025). "The effect of CENPN on nasopharyngeal carcinoma metastasis in vivo was tested in nude mice." (PMID 40458725, 2025).
nasopharyngeal carcinoma (continued). "CENPN is involved in the invasion and metastasis of nasopharyngeal carcinoma cells via USP37." (PMID 40458725, 2025). "However, the relationship between CENPN and the invasion and metastasis of nasopharyngeal carcinoma and its molecular mechanism remain unclear." (PMID 40458725, 2025). "Previously, we reported that centromere protein N (CENPN) is closely related to the pathogenesis, radiotherapy resistance and chemotherapy resistance of nasopharyngeal carcinoma, but the relationship between CENPN and nasopharyngeal carcinoma metastasis and its molecular mechanism are still unclear." (PMID 40458725, 2025). "The expression of CENPN, STAT3 and USP37 in metastatic tumors from nude mice and human nasopharyngeal carcinoma tissues was verified by immunohistochemistry and immunofluorescence staining." (PMID 40458725, 2025). "CENPN directly binds to STAT3 and promotes STAT3 phosphorylation and nuclear translocation to regulate USP37 transcription, thus promoting the invasion and metastasis of nasopharyngeal carcinoma." (PMID 40458725, 2025). "Furthermore, CENPN can interact with AKT and enhances its phosphorylation at S473, which promotes cell proliferation and cell cycle progressing of nasopharyngeal carcinoma cells." (PMID 37292517, 2023). "Centromere protein N (CENP-N) has been reported to be highly expressed in malignancies, but its role and mechanism in nasopharyngeal carcinoma (NPC) are unknown." (PMID 34893086, 2021).
oral squamous cell carcinoma (4 papers, 2021 to 2024). "In oral squamous cell carcinoma, CENPN knockdown arrests the cell cycle in the G1 phase, which leads to the suppression of cellular proliferation." (PMID 34646306, 2021).
colorectal cancer (3 papers, 2021 to 2024). A primary or metastatic malignant neoplasm that affects the colon or rectum.
glioma (3 papers, 2021 to 2025). A benign or malignant brain and spinal cord tumor that arises from glial cells (astrocytes, oligodendrocytes, ependymal cells). "GSEA results suggested that CENPN was associated with multiple molecular mechanisms of glioma development." (PMID 34646306, 2021). "This study showed that upregulated CENPN expression was associated with adverse clinical outcomes of glioma patients." (PMID 34646306, 2021). "Cell experiments showed that CENPN deficiency impaired cell proliferation, migration and invasion ability and increased glioma apoptosis." (PMID 34646306, 2021). "In addition, in vitro experiments showed that CENPN deficiency impaired the proliferation, migration and invasion and increased the apoptosis of glioma cell lines." (PMID 34646306, 2021). "Taking advantage of the substantial data gained from public databases, we performed comprehensive bioinformatic analyses for CENPN expression in glioma." (PMID 34646306, 2021). "In the present study, CENPN served as a prognostic biomarker for glioma based on data obtained from public cancer databases and clinical specimens." (PMID 34646306, 2021). "Knockdown of CENPN impaired the proliferation, migration and invasion and increased the apoptosis of glioma cell lines." (PMID 34646306, 2021). "Compared with the values in normal samples, the CENPN mRNA level was markedly higher in the glioma samples." (PMID 34646306, 2021). "In vitro experiments were conducted to investigate the impacts of CENPN on human glioma cells." (PMID 34646306, 2021). "Moreover, we investigated the potential functions of CENPN in the immune infiltration and immunoregulation of the glioma microenvironment." (PMID 34646306, 2021). "Additionally, several immune cell types, such as CD8+ T cells, macrophages and regulatory T cells (Tregs), were infiltrated in glioma cases with CENPN-high, while neutrophils, dendritic cells (DCs) and natural killer cells (NK cells) showed opposite trends." (PMID 34646306, 2021). "We found that CENPN was upregulated in 72.3% (81/112) of glioma tissues." (PMID 34646306, 2021). "Our study further evaluated the protein level of CENPN in 112 glioma specimens by IHC." (PMID 34646306, 2021). "However, the clinicopathologic significance and biological functions of CENPN in glioma are still unclear." (PMID 34646306, 2021). "Furthermore, wound healing and Transwell assays showed that downregulation of CENPN suppressed the migration and invasion ability of glioma cells compared with that in the siScr group." (PMID 34646306, 2021). "The mechanisms by which CENPN may immunomodulate the microenvironment of glioma remain to be understood." (PMID 34646306, 2021). "All in all, these findings indicate that CENPN might be a valid therapeutic target for glioma." (PMID 34646306, 2021). "The mRNA expression levels of CENPN in glioma were assessed based on GEPIA and GSE16011, a glioma dataset obtained from the Gene Expression Omnibus database." (PMID 34646306, 2021). "The results showed that upregulated CENPN expression was correlated with advanced clinicopathological parameters (age, grade, histological type and KPS, etc.)and represented an independent prognostic factor of glioma." (PMID 34646306, 2021). "However, the roles of CENPN in glioma have not been clarified." (PMID 34646306, 2021). "CENPN may not promote glioma cell progression by influencing the cell cycle; therefore, additional cell experiments are needed to clarify its specific functions in glioma." (PMID 34646306, 2021).
lung adenocarcinoma (3 papers, 2020 to 2023). A carcinoma that arises from the lung and is characterized by the presence of malignant glandular epithelial cells. "NDC80, CENPL, ORC1, CENPN, CCNE1, and CCNB2 were significantly upregulated in the TCGA cohort as well as in the 18 pairs of lung adenocarcinoma patient samples, and high expression was significantly associated with poor prognosis in lung adenocarcinoma." (PMID 37123398, 2023).
hepatocellular carcinoma (2 papers, 2021). A malignant tumor that arises from hepatocytes. "Most recently, CENPN was shown to promote hepatocellular carcinoma cell proliferation and CENPN deficiency was shown to increase radiotherapy-induced DNA damage." (PMID 34646306, 2021).
liver cancer (2 papers, 2021 to 2023). An epithelial or non-epithelial malignant neoplasm that arises from the liver. "GEPIA revealed that the overall survival (OS) and disease-free survival (DFS) of liver cancer patients with high CENPN expression were shorter than those of patients with low CENPN expression." (PMID 33987018, 2021). "Our results revealed that CENPN was highly expressed in liver cancer as well as affected the prognosis of patients." (PMID 33987018, 2021). "The results revealed that CENPN was highly expressed in liver cancer cells." (PMID 33987018, 2021).
ovarian carcinoma (2 papers, 2021 to 2024). A malignant neoplasm originating from the surface ovarian epithelium. "Our further qRT-PCR showed that seven hub genes (BUB1, KIF2C, NUP43, NDC80, NUF2, CCNB2 and CENPN) were differentially expressed in platinum-resistant ovarian cancer cells." (PMID 34820170, 2021). "For example, most ovarian cancer patients receive PTX chemotherapy, but only 42% of patients respond to PTX, and the relationship between CENPN and PTX resistance in ovarian cancer is also worthy of further study." (PMID 37776538, 2024).
Breast tumors (1 paper, 2023). "Breast tumors with CENPN overexpression appeared to be more amenable to immunotherapy, according to TIDE study." (PMID 37697245, 2023). "In TIDE, immunotherapy was more effective in treating breast tumors with high CENPN expression, raising the possibility that it could be used as a biomarker for predicting treatment effectiveness of immune checkpoint inhibitors and serve as a potential novel immunotherapy target." (PMID 37697245, 2023).
metastatic tumors (1 paper, 2025). "In vivo studies demonstrated a reduced number of liver metastatic tumors in mice injected with CENPN knockdown cells, with decreased expression levels of CENPN, p-STAT3, and USP37." (PMID 40458725, 2025).
nasopharyngitis (1 paper, 2024). An inflammatory process that affects the nasopharynx. "Immunohistochemical scoring of the tissue microarray (TMA) showed that the expression level of CENPN in the 99 NPC patients was significantly higher than that in the 32 nasopharyngitis (NPG) patients." (PMID 37776538, 2024).
stomach adenocarcinoma (1 paper, 2024). "In stomach adenocarcinoma, high expression of CENPN can be used as a novel biomarker for stomach adenocarcinoma, and silencing CENPN inhibits gastric adenocarcinoma cell proliferation through cell cycle protein E1." (PMID 38693472, 2024).